TTR (transthyretin)
Diseases named in the same sentence as TTR in open-access papers (continued):
Sharing a sentence is not in itself a finding about the gene and the disease.
depression (16 papers, 2012 to 2025). "It has been reported that transthyretin is associated with neurodegenerative disorders and psychiatric condition including major depressive disorder." (PMID 33451315, 2021). "TTR protein levels had previously been associated with depression, such that low levels of TTR have been correlated with high suicidal ideation and low 5-HIAA." (PMID 24795602, 2014). "Therefore, our results suggest that in IL-18-deficit conditions, TTR in the brain is one of the mediators causally related to depression, and AHSG in peripheral organs is one of the regulators inducing energy imbalance." (PMID 34708129, 2021). "Interestingly, TTR has been reported to be involved in cognition during aging and associated with depression." (PMID 30615651, 2019). "Intersecting 87 targets predicted by network pharmacology for PPT for depression with 350 DEGs from transcriptome sequencing yielded a total of three target genes (TTR, FOS, and KL)." (PMID 39062817, 2024). "Our study revealed that Ttr expression was commonly elevated in the hippocampus of these mice, and hippocampal TTR overexpression induced depression-like behavior." (PMID 36835151, 2023). "In preclinical studies using animal model of depression, administration of sodium butyrate, a histone deacetylase inhibitor with antidepressant-like effect, has resulted upregulation of transthyretin RNA level." (PMID 33451315, 2021). "The described results in this study are not clear enough to support a mechanism via blocked thyroid transporter TTR to explain depression after PCB exposure." (PMID 30884813, 2019). "Of note, reduced CSF levels of transthyretin (TTR), a major carrier of T4 in the BBB and blood-CSF barrier, has been implicated in depression and first-onset psychosis, respectively." (PMID 22937417, 2012). "An additional argument for the relevance of abnormal HPT function in depression is the finding that MDD patients exhibit significantly reduced blood levels of transthyretin (TTR), the protein thought to be partially responsible for thyroxine transport across the blood brain barrier." (PMID 36453495, 2023). "Then, we identified 16 molecules that might cause the depressive characteristics of Il18−/− mice; in particular, decreased TTR in the PFC might be a mediator for developing depression." (PMID 34708129, 2021). "Whether the function of TTR in cognition and depression is mediated by the regulation of the δ-GABAA-Rs reported here will be an interesting topic to explore in future studies." (PMID 30615651, 2019). "Patients with major depression have a lower TTR level in the CSF than healthy controls." (PMID 30884813, 2019). "Thus, lower TTR of the PFC in Il18−/− mice might be a mediating factor of depression." (PMID 34708129, 2021). "TTR has been established as neuroprotective with increased expression in the prefrontal cortex of male but not female patients with depression." (PMID 41331623, 2025). "Our data suggest that PPT may achieve the treatment of depression by inhibiting the expression of FOS, enhancing the expression of TTR and KL, and modulating the PI3K-AKT signaling pathway." (PMID 39062817, 2024). "We concluded that PPT might be therapeutic in depression through the PI3K-AKT signaling pathway and unearthed three key targets (TTR, FOS, and KL)." (PMID 39062817, 2024). "In this study, we found that behavioral symptoms of depression on mice models with the decrease of BrdU/NeuN- and Dcx-positive populations and MAP-2 expression in hippocampus were induced by cranial irradiation, and transthyretin (TTR) was highly expressed in hippocampus after irradiation." (PMID 29849106, 2018). "Moreover, we are mindful that in our sample, neither transthyretin or PE034:3(16:1/18:2) levels were significantly associated with depressive symptomology and more work is needed to substantiation these findings in the context of depression." (PMID 35794184, 2022).
depression (continued). "TTR is drastically reduced in the hippocampus of selectively-bred Wistar Kyoto More Immobile (WMI) males, who exhibit depression-like behaviors, unlike the control Wistar Kyoto Less Immobile (WLI) rats." (PMID 36453495, 2023).
Hypertension (15 papers, 2009 to 2025). The presence of chronic increased pressure in the systemic arterial system. "In addition, the administration of transthyretin from preeclamptic serum into pregnant IL10−/− mice induced the hallmark symptoms of preeclampsia (hypertension, proteinuria, glomerular endotheliosis, fetal growth restriction [FGR]) whereas, transthyretin from control serum did not17." (PMID 28751735, 2017). "In fact, our prior studies have demonstrated that human TTR-overexpressing transgenic mice manifest a robust deposition of TTR aggregates in the placenta and PE-like features, including hypertension, proteinuria, and the release of anti-angiogenic factors." (PMID 37626934, 2023). "Our prior studies have demonstrated that TTR misfolding and aggregation contribute to the pathogenesis of preeclampsia (PE), a pregnancy-specific, multifactorial syndrome characterized by hypertension after 20 weeks of gestation." (PMID 37626934, 2023). "To further clarify the therapeutic mechanisms of TTR on pregnant hypertension, we investigated the MMP‐2 and MMP‐9 expressions in placental tissues." (PMID 32533762, 2020). "This study found that the placental and fetal weights increased after TTR treatment in pregnant hypertension rat models." (PMID 32533762, 2020). "The TTR levels in placenta tissues were then detected by western blot to monitor the changes of TTR during pregnant hypertension." (PMID 32533762, 2020). "Based on the establishment of the effective animal model of hypertensive disorders complicating pregnancy, the effects of TTR on PE were further analyzed in the next study." (PMID 32533762, 2020). "Compared with the control, the placental and fetal weights in the l‐NAME group effectively were lower, but such effects could be rescued by TTR treatment in the pregnant hypertension rat model." (PMID 32533762, 2020). "Our results showed that TTR could effectively reverse the increase of blood pressure and urine protein in pregnant rats with hypertension." (PMID 32533762, 2020). "The results showed that MMP‐2 and MMP‐9 levels in the pregnant hypertension rats were significantly reduced compared with those in the healthy pregnant rats, but such effects could be significantly rescued by TTR treatment (P < 0.05)." (PMID 32533762, 2020). "Furthermore, we investigated the placental and fetal weights of pregnant hypertension rats after TTR injection." (PMID 32533762, 2020). "In addition, the results from ELISA and western blot showed that the concentrations of TTR in pregnant rats with hypertension were significantly lower than those in normal pregnant rats, suggesting that TTR might be a novel candidate biomarker for PE." (PMID 32533762, 2020). "First, ELISA was performed to quantify the serum TTR levels in the l‐NAME and control groups, and the results showed that TTR levels in the pregnant hypertension rats were significantly reduced compared with those in the healthy pregnant rats." (PMID 32533762, 2020). "Because the results were not changed, no additional adjustment was made for hypertension, BMI, smoking or use of oral snuff, even though they were statistically significantly related to TTR concentrations." (PMID 19383125, 2009).
restrictive cardiomyopathy (15 papers, 2021 to 2025). A type of heart disorder referring to the inability of the ventricles to fill with blood because the myocardium (heart muscle) stiffens and looses its flexibility. "Transthyretin amyloid cardiomyopathy (ATTR-CM) is a progressive form of restrictive cardiomyopathy caused by the misfolding and deposition of transthyretin protein." (PMID 40943848, 2025). "Mechanistically, ATTR-wt leads to the deposition of non-mutated TTR protein in the myocardial extracellular space, leading to restrictive cardiomyopathy, arrhythmias, and heart failure." (PMID 41295360, 2025). "Of the remaining 144 patients, who neither belonged to an ATTRv family, nor were carrying a TTR mutation 134 had a late-onset axonal polyneuropathy, while the other 10 displayed restrictive cardiomyopathy with infiltrative features." (PMID 35463150, 2022).
schizophrenia (15 papers, 2007 to 2023). A major psychotic disorder characterized by abnormalities in the perception or expression of reality. "For instance, patients with schizophrenia have been found to have reduced levels of transthyretin and altered nicotinic receptor signaling has been associated with schizophrenia in humans and animal models, suggesting a potential relevance of choroid plexus function in the disease state." (PMID 31119189, 2019). "Seven genes were investigated and involved in the synthesis, degradation and transportation of RA, ALDH1A1, ALDH1A2, ALDH1A3, CYP26A1, CYP26B1, CYP26C1 and Transthyretin (TTR), for their roles in the development of schizophrenia." (PMID 24564241, 2013). "Besides the serum concentration of thyroid hormones, the dysregulation of transthyretin plays several roles in neurobiological function of schizophrenia, including neurodevelopment and endocrine disruption." (PMID 32174848, 2020). "Also, different levels of TTR in other disease like familial amyloid, senile systemic amyloidosis and schizophrenia, and its altered level in human carotid atherosclerotic tissues were also reported." (PMID 33299376, 2020). "On the other hand, as transthyretin is a thyroid hormone-binding protein that transports thyroxine from the bloodstream to the brain, the decreased level of transthyretin in CSF could imply abnormalities in thyroxine transport in brains of schizophrenia patients." (PMID 17712404, 2007). "The most important factors contributing to the partial separation between schizophrenia patients and controls were the VGF23-62 peptide (at m/z = 3,959) and transthyretin proteins (at m/z = 13.7−14.0k)." (PMID 17712404, 2007). "Recently, it has been reported that TTR can play roles independent of its ligands, spanning from neuroprotection in Alzheimer and schizophrenia to the involvement in memory and learning." (PMID 30131519, 2018).
amyotrophic lateral sclerosis (14 papers, 2008 to 2025). Amyotrophic lateral sclerosis (ALS) is a neurodegenerative disease characterized by progressive muscular paralysis reflecting degeneration of motor neurons in the primary motor cortex, corticospinal tracts, brainstem and spinal cord. "This category covers disorders such as Parkinson's disease (PD), Alzheimer's disease (AD), Creutzfeldt-Jakob's, Amyotrophic Lateral Sclerosis (ALS) or Transthyretin (ATTR) amyloidosis." (PMID 39582896, 2024). "Reduced CSF TTR levels have also been reported in patients with depression (although not in those who committed suicide), normal pressure hydrocephalus and most recently in amyotrophic lateral sclerosis (ALS)." (PMID 22112803, 2011). "TTR is a known negative acute phase protein that is significantly reduced in the CSF of amyotrophic lateral sclerosis patients." (PMID 19710940, 2009).
glaucoma (14 papers, 2008 to 2024). Increased pressure in the eyeball due to obstruction of the outflow of aqueous humor. "Surprisingly, we found an association of the V122I TTR pQTL with primary angle closure glaucoma." (PMID 39316441, 2024). "Interfering protein precipitations of TTR might cause a mechanical barrier for aqueous fluid that could consequently lead to glaucoma in some patients." (PMID 18682810, 2008). "Aqueous humor from the cataract and glaucoma controls showed similar TTR levels, with the latter displaying slightly higher values, in line with the literature (+10.5% compared to cataract control)." (PMID 37357518, 2023). "Aqueous humor for patient 1 showed slightly lower TTR levels (-34.9% compared to cataract control), whereas aqueous humor in patient 2 was similar to cataract (+8.1%) and glaucoma controls (-2.1%)." (PMID 37357518, 2023). "The amount of TTR, expressed as TTR/Ponceau S ratio, was 0.032 in the HC serum, 0.095 in glaucoma aqueous humor and 0.086 in cataract aqueous humor controls." (PMID 37357518, 2023). "As a proof of concept, the use of a five-protein panel, consisting of C4a, CFH, FCN3, APOA4, and TTR predicts the transition to glaucoma disease in 78% of cases." (PMID 32585848, 2020). "The study described here therefore continued our evaluation of the efficacy of trabeculectomy with MMC in patients with glaucoma secondary to TTR-related FAP." (PMID 24802803, 2014). "Dry eye is an early autonomic symptom of TTR-FAP, and a decrease in visual acuity induced by vitreous opacity or glaucoma is recognized as TTR-FAP progresses." (PMID 23425518, 2013). "Possibly dying retinal ganglion cells in glaucoma patients dispense their TTR in the AH, which leads to higher TTR concentrations in patients." (PMID 18682810, 2008). "One of the proteins that is highly abundant in the aqueous of glaucoma patients was identified as transthyretin." (PMID 18682810, 2008). "These biomarkers were purified further, and one marker, which was upregulated in glaucoma patients (p=0.006), was identified as transthyretin." (PMID 18682810, 2008). "Moreover, the five-protein panel consisting of complement C4a, complement factor H, ficolin-3, apolipoprotein A4, and transthyretin predicted the transition to glaucoma in 78% of cases, and to the advanced disease in 89%." (PMID 32585848, 2020). "Moreover, the five-protein panel, consisting of C4a, CFH, FCN3, APOA4, and TTR, predicted the transition to glaucoma in 78% of cases and correctly classified 89% of cases with advanced glaucoma in this animal model." (PMID 32585848, 2020). "Transthyretin might play a role in the onset of glaucoma since it has been shown to form amyloid deposits." (PMID 18682810, 2008). "Our findings of increased levels of TTR in the aqueous humor of glaucoma patients indicate that this protein might play a role in the pathogenesis of glaucoma." (PMID 18682810, 2008). "However, glaucoma has not been a prominent feature in prior descriptions in individuals with the TTR V1221 variants, who are particularly susceptible to developing cardiovascular and neurologic disease." (PMID 39316441, 2024). "Unlike other TTR variants, ocular manifestations were also rare; only patient 5 had glaucoma." (PMID 28882124, 2017). "Interestingly, in contrast to other organs where the mutated TTR deposits disappear after liver transplantation, the risk of glaucoma does not decrease after liver transplantation in patients." (PMID 23028713, 2012). "For glaucoma, PTGDS, GSTP1, SPD1, and CST3 were expressed significantly higher in almost all tissues; CRP, ALB, and TTR were markedly increased in the liver; MBP and TF exhibited high expression in the brain." (PMID 37052519, 2023). "Patients with TTR-related FAP commonly have ocular manifestations, especially vitreous opacity and glaucoma, which are troublesome and can restrict the daily lives of patients; these ocular involvements occur more frequently during the course of the illness." (PMID 24802803, 2014).
glaucoma (continued). "Interestingly, we could detect elevated transthyretin concentrations in glaucoma samples." (PMID 18682810, 2008). "Aqueous humor TTR levels showed mild-to-no reduction in treated patients compared to non-amyloidotic subjects with cataracts (-34.9% and +8.1%, respectively) and glaucoma (-41.1% and -2.1%)." (PMID 37357518, 2023). "TTR synthesis was demonstrated to decrease non-amyloidotic primary congenital glaucoma and increase primary open-angle glaucoma." (PMID 37357518, 2023). "Besides, TTR and ITIH4 have been previously identified altered in the human aqueous humor of glaucoma patients." (PMID 32585848, 2020). "Furthermore, patisiran failed to reduce TTR levels in the aqueous humor of the ATTR-v patient with glaucoma, which should increase barrier permeability." (PMID 37357518, 2023).
plasma cell dyscrasia (14 papers, 2015 to 2025). "95% of CA is either from misfolded mutant or wild-type transthyretin (TTR) protein, or light chain (AL) fragments from immunoglobulins and plasma cell dyscrasia." (PMID 40799850, 2024). "This approach is certainly more specific and less time‐consuming, as Perugini 1 patients should always undergo biopsy confirmation also in the absence of plasma cell dyscrasia, but may have caused some CA diagnoses to be missed (especially non‐TTR‐CA cases)." (PMID 34390490, 2021). "Bone scintigraphy with exclusion of a plasma cell dyscrasia can diagnose transthyretin-related cardiac amyloid noninvasively, for which novel treatments are emerging." (PMID 32771574, 2020).